NLRP3 (NLR family pyrin domain containing 3)
Diseases named in the same sentence as NLRP3 in open-access papers (continued):
Sharing a sentence is not in itself a finding about the gene and the disease.
myocardial infarction (continued). "Mcc950, which is a novel inhibitor of the NLRP3 inflammasome, can be applied to treat various kinds of cardiovascular diseases, such as atherosclerosis and myocardial infarction." (PMID 37008319, 2023). "A major perpetrator of inflammatory damage in both acute myocardial infarction and CKD, NLRP3 activation is linked to renal injury-induced cardiac dysfunction, and induction of a pro-inflammatory phenotype." (PMID 37770948, 2023). "The inhibition of NLRP3 inflammasome activation after myocardial infarction proves beneficial in reducing infarct size and preserving cardiac function." (PMID 37763063, 2023). "Increasing evidence showed that NLRP3 inflammasome was a potential therapeutic target for IRI in myocardial infarction." (PMID 37008319, 2023). "It inhibited NLRP3, IL-1β, and caspase-1 expression in myocardial tissue three days after myocardial infarction." (PMID 36320147, 2022). "Treatments inhibiting the activation of NLRP3 contributed to improved cardiac function and remodeling in the mice with myocardial infarction and cardiac hypertrophy." (PMID 35647084, 2022). "NLRP3 inhibitor can significantly reduce myocardial infarct area, maintain cardiac function, and inhibit the overactivation of NLRP3 inflammasome of AMI animal models." (PMID 35615687, 2022). "The activation of NLRP3 can accelerate cardiac remodeling and cardiac function disorders after myocardial infarction." (PMID 35401934, 2022). "NLRP3 inflammasome senses intracellular signaling during tissue ischemia and provokes immune response during acute myocardial infarction." (PMID 36145367, 2022). "A recent study showed that GSK-3β inhibition alleviated NLRP3 inflammasome activation in myocardial infarction, and subsequently affected IL-1β release." (PMID 36164369, 2022). "AAV9-si-Dectin-1 improved cardiac contractility 21 days after myocardial infarction and inhibited NLRP3 expression, preventing cardiac fibrosis seven days after CAO." (PMID 36320147, 2022). "Researchers reported that after myocardial infarction, NLRP3 inflammasome components were primarily upregulated in left ventricle and mainly distributed in myocardial fibroblasts." (PMID 36164369, 2022). "We based the dose of colchicine used in this study on that found to downregulate proinflammatory cytokines, limit the NLRP3 inflammasome, improve cardiac function, and increase survival after myocardial infarction in a past study." (PMID 36262119, 2022). "The purpose of this study was to investigate the effects of the NLRP3-inflammasome inhibitor IZD334 on cardiac damage in a pig model of myocardial infarction." (PMID 36551811, 2022). "TanIIA was shown to block the NLRP3 inflammasome in a canine myocardial infarction model by restoring JAK-STAT and insulin signaling in the heart." (PMID 35432718, 2022). "NLRP3-inflammasome-mediated signaling is thought to significantly contribute to the extent of myocardial damage after myocardial infarction (MI)." (PMID 36551811, 2022). "INF4E, a newly synthesized small-molecule inhibitor of NLRP3 inflammasome, significantly reduces myocardial infarct size and LDH release and attenuates the formation of NLRP3 inflammasome in a time-dependent manner." (PMID 36555757, 2022). "Following myocardial infarction, caspase-1 activity was increased and the inflammasome was formed in heart tissue; NLRP3 silencing or pharmacologic inhibition prevented inflammasome formation and limited infarct size and cardiac enlargement." (PMID 34776995, 2021). "After acute myocardial infarction, IL-17A aggravates inflammatory response and ischemic injury by inducing macrophages infiltration, and NLRP3 inflammasome and p38 MAPK are significantly activated." (PMID 33171330, 2021). "The NLRP3 inflammasome, caspase-1, and IL-1β are found to be upregulated in peripheral neutrophils from patients with acute myocardial infarction." (PMID 34776995, 2021).
myocardial infarction (continued). "In a murine myocardial infarct model, with doses comparable to those employed in humans (0.1 mg/kg), colchicine attenuated the activation of NLRP3 inflammasome constituents over and above the decrement in inflammatory mediators." (PMID 34443594, 2021). "For instance, Nicorandil suppresses TLR4/MyD88/NF-κB/NLRP3 axis to alleviate pyroptosis in rats with myocardial infarction." (PMID 34595225, 2021). "Transplantation of bone marrow from Nlrp3–/– mice reduced adverse cardiac remodeling following myocardial infarction compared to bone marrow from wild-type mice, suggesting that NLRP3 activation in infiltrated hematopoietic cells increases cardiac remodeling." (PMID 34776995, 2021). "In conclusion, herein, we illustrated for the first time that inhalation of H2 ameliorates myocardial infarction‐induced cardiac remodelling and fibrosis in MI rats and exert its protective effect mainly through inhibiting NLRP3‐mediated pyroptosis." (PMID 34402164, 2021). "The NLRP3 inhibitor MCC950 suppressed myocardial infarction-induced NLRP3 inflammasome activation, alleviated cardiac inflammation and fibrosis, and improved cardiac function." (PMID 34776995, 2021). "The Nlrp3 inflammasome has been shown to be involved in the development of cardiac contractile dysfunction in a CKD model; the Nlrp3 inflammasome also plays a key role in myocardial fibroblasts after myocardial infarction." (PMID 33628380, 2021). "The expression of NLRP3, IL‐1β, and IL‐18 mRNA was found to be increased in cardiac tissue post myocardial infarction, and expression in non‐cardiomyocytes altered more dramatically in an NF‐κB–dependent manner." (PMID 32508013, 2020). "Further, a large body of evidence underscores the critical contribution of NLRP3 inflammasome in acute myocardial infarction and its consequences on adverse cardiac remodeling and heart failure." (PMID 32867797, 2020). "In particular, the NACHT, LRR, and PYD domain-containing protein 3 (NLRP3) inflammasome is thought to act as a central player in the setting of acute myocardial infarction (AMI) and heart failure." (PMID 31963447, 2020). "Cardiomyopathy and myocarditis, along with myocardial infarction, induce HF via myocardium morbidity, and NLRP3 inflammasome contributes to such myocardium morbidity‐induced HF." (PMID 32508013, 2020). "The NACHT, LRR, and PYD domain-containing protein 3 (NLRP3) inflammasome was largely studied in the CV field, as confirmed by their role in atherosclerosis, acute myocardial infarction, heart failure, and pericarditis." (PMID 31963447, 2020). "The activation of NLRP3 inflammasome and the release of IL-1β are known to accelerate tissue damage and abnormal remodeling process through NLRP3/TGF-β/Smad pathway in cardiac fibroblasts after myocardial infarction." (PMID 33126764, 2020). "Data on the role of the NLRP3 inflammasome in patients with an acute myocardial infarction or other inflammatory diseases are still scarce." (PMID 31672136, 2019). "In conclusion, the current study provides primary evidence that EP's beneficial effect on myocardial infarction involves inhibition of NLRP3 inflammasome activation." (PMID 30728885, 2019). "The NLRP3 inflammasome is activated in the ischemic heart and the inhibition of the NLRP3-initiated inflammasome during experimental myocardial infarction minimizes the activation of caspase-1 in the heart and improves LV remodeling and function." (PMID 29371912, 2017). "The present study improves our understanding on the effects of the NLRP3 inflammasome targeting in acute myocardial infarction." (PMID 28053692, 2016). "Hypericin, a major active constituent of Hypericum perforatum, has been shown to upregulate autophagy after myocardial infarction, thereby inhibiting the NLRP3 inflammasome pathway, alleviating myocardial hypertrophy, and reducing fibrinogen deposition, ultimately exerting cardioprotective effects." (PMID 41179812, 2025).
myocardial infarction (continued). "Furthermore, isofraxidin mitigates myocardial infarction by inhibiting the expression of NLRP3 inflammasome, which induces pro-inflammatory cytokine expression." (PMID 40149629, 2025). "Notably, pharmacological GSK3β inhibition was shown to markedly improve myocardial dysfunction and prevent remodelling in a rat model of myocardial infarction through reducing NLRP3 inflammasome activation." (PMID 39392548, 2025). "Importantly, KLX can ameliorate myocardial infarction-induced cardiac damage by inhibiting the expression of the NLRP3 inflammasome, reducing the release of proinflammatory cytokines IL-1β and IL-18, and suppressing pyroptotic cell death." (PMID 40148674, 2025). "Interestingly, the effects of NLRP3 inflammasome seem attenuated in the acute phase of myocardial infarction, modulated by enzymes released by monocytes, avoiding excessive inflammatory stimuli." (PMID 40756604, 2025). "In addition, macrophage-derived EVs enriched in miR-378a-3p have been shown to regulate cell death by blocking activation of the NLRP3/Caspase-1/GSDMD pathways in cardiomyocytes after myocardial infarction." (PMID 40496017, 2025). "Short-term inhibition of the NLRP3 inflammasome could theoretically be beneficial in acute inflammatory events such as acute myocardial infarction." (PMID 40835597, 2025). "In summary, we demonstrated that Coenzyme Q10 treatment can effectively promote the recovery of cardiac function after myocardial infarction and prevent its progression to heart failure, partially through inhibiting NLRP3/IL1β pathway-mediated inflammation in macrophages." (PMID 38281937, 2024). "The use of the covalent NLRP3 inhibitor oridonin preserved left ventricular ejection fractions and fractional shortening, and it also markedly limited the myocardial infarct size in surgically induced myocardial infarction in mice." (PMID 39594530, 2024). "Having demonstrated the role of CoQ10 on the activation of the NLRP3/IL1β pathway and downstream inflammatory response in macrophages, we next explored the impact of CoQ10 on macrophage-mediated inflammation in the context of myocardial infarction." (PMID 38281937, 2024). "The NLRP3 and caspase-1 expression are increased in myocardial infarction, and knock-out of NLRP3 could reduce infarct size in different in vivo and ex vivo models of ischemia/reperfusion." (PMID 38716981, 2024). "Activation of both NLRP3 inflammasome and caspase-11 inflammasome lead to the secretion of potent proinflammatory cytokines, IL-1beta and IL-18, which are well recognized as potential therapeutic targets for acute myocardial infarction." (PMID 37108494, 2023). "In addition, by inhibiting the expression of NLRP3, the inflammatory response after myocardial infarction can be reduced, which can protect myocardial function and improve myocardial remodeling." (PMID 38268894, 2023). "A recent study has shown that SF3A2 as new susceptibility gene for myocardial infarction.In our study, proteome and experimental data identified that SF3A2 could positively regulate NLRP3 inflammasome activation and cell pyroptosis." (PMID 36732831, 2023). "The role of NLRP3 in myocardial infarction is controversial." (PMID 36835212, 2023). "FTZ could preserve cardiac function resulting from ischemic insult by inhibiting pyroptosis, which was partially reversed by NLRP3 overexpression, indicating that NLRP3 could be a potential target of FTZ in treating myocardial infarction." (PMID 36387353, 2022). "Recently, adapters that inhibit the NLRP3 inflammasome and inhibitors that utilize NLRP3 inflammasomes were shown to be beneficial in reducing the myocardial infarct size and improving cardiac function in animal studies, and early clinical trials are expected to show their effectiveness." (PMID 35620580, 2022). "Notably, these findings are in line with the reported NLRP3 inflammasome inhibition by linagliptin in a rodent model of myocardial infarction." (PMID 35890148, 2022).
myocardial infarction (continued). "In addition, the NLRP3 inflammasome releases mature IL-1β and IL-18 in response to oxidative stress and danger signals upon myocardial infarction." (PMID 35432718, 2022). "In another study that the mice underwent permanent CAO, myocardial infarction promoted cardiac contractile dysfunction, and left ventricular myocardial fibrosis, and increased the amount of NLRP3, cleaved caspase-1, cleaved IL-1β, cleaved IL-18 in left ventricular tissue for four weeks." (PMID 36320147, 2022). "We proposed that OLT1177® (dapansutrile), a novel NLRP3 inhibitor, could preserve contractile reserve and diastolic function after myocardial infarction (MI)." (PMID 34207886, 2021). "Before being identified as a NLRP3 inhibitor, Tranilast showed beneficial effects in cardiac fibrosis and remodeling in several animal models of hypertension, diabetic cardiomyopathy and myocardial infarction." (PMID 33673188, 2021). "In addition, preclinical studies highlight the role of the NLRP3 inflammasome in ischemia reperfusion injury after an acute myocardial infarction, but contradictory results have been reported as well." (PMID 32648087, 2021). "Moreover, the NLRP3 inflammasome promotes tissue damage following acute organ injury, such as acute myocardial infarction (AMI)." (PMID 33673188, 2021). "Increasing evidence suggests that inhibition of the TLR4/MyD88/NF-κB/NLRP3 inflammasome pathway may reduce myocardial infarction-induced pyroptosis." (PMID 34595225, 2021). "NLRP3 inhibitors have shown promising results in animal models of myocardial infarction." (PMID 34135690, 2021). "The NLRP3 inflammasome plays an important role in the pathogenesis of some cardiovascular diseases, such as myocardial ischemia/reperfusion injury, acute myocardial infarction, and ventricular remodeling after myocardial infarction." (PMID 34093086, 2021). "Activated NLRP3 inflammasome is an important promoter gene of heart failure, and its downstream inflammatory factor IL‐1β has been used as an important target for the treatment of myocardial infarction in clinical trials." (PMID 34402164, 2021). "Moreover, activation of NLRP3 during myocardial infarction in cells other than myocytes (including endothelial cells, neutrophils, and fibroblasts) has been shown to contribute indirectly to cardiac dysfunction." (PMID 34685553, 2021). "CQ could abrogate the inhibitory effect of metformin on NLRP3 expression in a mouse model of acute myocardial infarction." (PMID 33584302, 2020). "It remained unclear whether pre‐treated hosts with n‐butylidenephthalide can rejuvenate the ageing heart and improve hADSC engraftment by regulating the ROS/NLRP3 inflammasome‐mediated cardiac fibrosis after myocardial infarction." (PMID 33022900, 2020). "NLRP3 (Nucleotide-binding oligomerization domain-like receptor pyrin domain-containing 3) inflammasome-mediated cardiomyocytes pyroptosis plays a crucial part in progression of acute myocardial infarction (MI)." (PMID 33100331, 2020). "Another study has reported that the inhibition of NLRP3-inflammasome could decrease the incidence of myocardial infarction and improve myocardial function in animal myocardial infarction models." (PMID 32595731, 2020). "Previous studies showed that inhibition or deletion of NLRP3 inflammasome could reduce myocardial infarction size and improve cardiac function in experimental animal models." (PMID 32848777, 2020). "The miR-133b/NLRP3 pathway might be helpful for developing novel treatment strategy of myocardial infarction." (PMID 31885905, 2019). "As has been elegantly reviewed by Toldo and Abbate20, recent experimental studies have focussed on the NLRP3 inflammasome as an important new therapeutic target to reduce reperfusion injury, infarct size, and prevent the development of HF following myocardial infarction." (PMID 31602405, 2019).
myocardial infarction (continued). "In regard to the treatment of I/R injury, a novel small molecule named 16673-34-0 was identified as an effective pharmacological agent to reduce NLRP3 inflammasome activation in cardiomyocytes and decrease the infarct size in a mouse model of acute myocardial infarction (AMI)." (PMID 29850631, 2018). "Indeed, in the setting of acute experimental myocardial infarction, NLRP3 deletion or pharmacological inhibition reduced infarct size, whilst activation of NLRP3 led to inflammasome hyperactivation and amplified cardiac injury." (PMID 29515457, 2018). "They found that in acute myocardial infarction (MI) with reperfusion and in a model of non-ischemic injury induced with doxorubicin, the inhibition of NLRP3 inflammasome cause a significantly reduction of infarct size and preserved systolic function." (PMID 29375564, 2017). "Interestingly, genetic modulation of NLRP3 has been reported to reduce myocardial infarct sizes upon IR." (PMID 28053692, 2016). "The functionally well-known Q705K polymorphism (rs35829419) in the NLRP3 gene was found to confer protective effect on AD, celiac disease, and female myocardial infarction but not on T1D or RA." (PMID 25788762, 2015). "However, after myocardial infarction, cardiac fibroblasts can transfer damaged mitochondrial components through MitoEVs, promoting macrophage inflammatory activation and exacerbating maladaptive ventricular remodeling through NLRP3 activation." (PMID 40867590, 2025). "Following myocardial infarction (MI), myocardial injury triggers the activation of the NLRP3 inflammasome, which exacerbates the myocardial inflammatory response, leading to enlargement of the infarct and worsening of cardiac dysfunction." (PMID 39925805, 2025). "The NACHT, leucine-rich repeat, and pyrin domain–containing protein 3 (NLRP3) inflammasome plays an essential role in myocardial infarction (MI) development." (PMID 40018377, 2025). "The re-purposing of existing drugs, such as colchicine and disulfiram, and the development of new, specific NLRP3 inhibitors represent a promising pipeline toward finally achieving clinically relevant cardioprotection that enhances the prognosis in patients suffering from myocardial infarction." (PMID 41487823, 2025). "Numerous studies, particularly in areas including myocardial infarction (MI), as well as heart failure, have illuminated the crucial role of interfering with the NLRP3 pathway in mediating therapeutic effects through the ANS." (PMID 38650918, 2024). "Furthermore, circHelz in vivo essays demonstrated a regulation of the miR-133/NLRP3 (NLR family protein pyrin domain containing 3) axis, leading to low levels of NLRP3 inflammasome that, therefore, decreased myocardial infarct size, pyroptosis, and inflammation and increased cardiac function." (PMID 36975887, 2023). "Moreover, another study showed that nicorandil could alleviate pyroptosis in rats with myocardial infarction by influencing the TLR4/MYD88/NF-κB/NLRP3 pathway." (PMID 38095638, 2023). "However, more evidence suggested that mechanism by which the NLRP3 inflammasome induces myocardial infarction expansion and cardiomyocyte death may be through pyroptosis rather than IL-1β production." (PMID 37957640, 2023). "Therefore, the targeted therapy of NLRP3 inflammasome may be a feasible strategy to reduce the area of myocardial infarction and prevent heart failure after acute myocardial infarction." (PMID 36378463, 2023). "Furthermore, NLRP3 inhibition ameliorated cardiac dysfunction induced by myocardial infarction." (PMID 35287557, 2022). "NLRP3 inflammasome activation mainly occurs in cardiac fibroblasts during myocardial remodeling and repair, activates IL-1β release and pyroptosis in cardiac fibroblasts after myocardial infarction (MI).A significant increase in expression of pyroptosis and MMP9 in cardiac fibrosis in diabetes." (PMID 35509275, 2022).